APP (amyloid beta precursor protein)
Diseases named in the same sentence as APP in open-access papers (continued):
Sharing a sentence is not in itself a finding about the gene and the disease.
Alzheimer disease (continued). "The Alzheimer's disease (AD) research community has historically used first‐generation transgenic (Tg) mouse models that overexpress proteins linked to familial AD (FAD), mutant amyloid precursor protein (APP), or APP and presenilin (PS)." (PMID 28768718, 2017). "This study assesses whether C-terminal fragments (CTF) of the amyloid precursor protein (APP) are present in cerebrospinal fluid (CSF) and their potential as biomarkers for Alzheimer’s disease (AD)." (PMID 28559572, 2017). "It is widely accepted that amyloid β (Aβ) generated from amyloid precursor protein (APP) oligomerizes and fibrillizes to form neuritic plaques in Alzheimer’s disease (AD), yet little is known about the contribution of APP to intracellular signaling events preceding AD pathogenesis." (PMID 28374012, 2017). "For instance, in hippocampal CA1 and cortex regions of PS1/APP mice, a rodent model of Alzheimer's disease (AD), the nuclear concentration of Beclin 1 was detected in a large proportion of neurons, compared with the cytosolic expression of Beclin 1 in the neurons of age-matched control brain." (PMID 28383560, 2017). "The Tg(PDGFB-APPSwInd)20Lms (MGI:3057148, here referred to as ‘J20’) mouse model is a transgenic animal that overexpresses mutant human APP protein (amyloid precursor protein), and is widely used as a model of amyloid deposition and pathogenesis in the study of Alzheimer’s disease (AD)." (PMID 29062914, 2017). "Both lines of evidence suggest that APP cleavage is a central event in Alzheimer’s disease." (PMID 26216398, 2016). "Alzheimer’s disease (AD) is the most prevalent form of dementia characterized by the extracellular accumulation of amyloid β (Aβ) peptides, which are produced by proteolytic cleavages of amyloid precursor protein (APP)." (PMID 27687691, 2016). "Taken together, our findings offer a new perspective on the physiological function of APP in the central nervous system and may provide a molecular link to the pathogenesis of Alzheimer’s disease." (PMID 27092780, 2016). "The phosphorylation status of Mint1 could impact on the pathological trafficking of APP in Alzheimer's disease." (PMID 26865271, 2016). "Detailed molecular analyses in mice and cells led to the findings that in Alzheimer’s disease Pin1 regulates amyloid precursor protein (APP) processing and amyloid-beta production while it is required for Tau dephosphorylation and correct neurofibrillary organization." (PMID 27199664, 2016). "This demonstrates that reducing APP trafficking to lysosomes may be a strategy to reduce Aβ 42 in Alzheimer’s disease." (PMID 27776132, 2016). "In Alzheimer’s disease Pin1 participates in APP processing and neurofibrillary tangle formation." (PMID 27199664, 2016). "The serial proteolysis of the amyloid precursor protein (APP) by β- and γ-secretase results in the generation of a ~4kDa peptide termed Aβ, the main component of senile plaques accumulating in the brain of subjects affected by Alzheimer’s disease." (PMID 27192432, 2016). "Our previous studies on p25 dysregulation put forward the hypothesis that CYFIP2 expression is reduced in Alzheimer’s disease and that this contributes to memory impairment, abnormal APP processing and tau hyperphosphorylation." (PMID 27524794, 2016). "Because higher levels of APP have been correlated with Alzheimer's disease and Down syndrome, we asked whether levels of APL‐1, the C. elegans APP‐related protein, have an effect on lifespan." (PMID 27557896, 2016). "It has been suggested that KLK6 may process APP and this way contributes to Alzheimer’s disease pathology." (PMID 27186164, 2016). "Alzheimer's disease (AD) is histopathologically characterized by neurodegeneration, the formation of intracellular neurofibrillary tangles and extracellular Aβ deposits that derive from proteolytic processing of the amyloid precursor protein (APP)." (PMID 27470171, 2016).
Alzheimer disease (continued). "Importantly, it has a pathological role in Alzheimer disease (AD) as it generates the neurotoxic amyloid β-peptide from the amyloid precursor protein (APP)." (PMID 27036709, 2016). "Another major substrate of ADAM10 is the amyloid precursor protein (APP) for which ADAM10 acts as the constitutive alpha-secretase and thus possesses the ability to prevent the generation of the pathogenic Aβ peptide in Alzheimer’s disease (AD)." (PMID 26802628, 2016). "Despite the importance of APP in Alzheimer's disease it still remains unclear what exactly the physiological function of this molecule is." (PMID 26125944, 2015). "The amyloid precursor protein (APP) is a key molecule in Alzheimer disease." (PMID 25880931, 2015). "During HAART therapy HIV persists in the brain and local inflammatory responses to the virus can lead to higher APP production and β-amyloid deposition which may lead to the progression of Alzheimer’s disease and HAND." (PMID 26793166, 2015). "PSEN1 encodes a protein that regulates the processing of amyloid precursor protein (APP) and is mutated in familial forms of Alzheimer’s disease while DPF3 function is associated with the BAF chromatin remodeling complex to promote transcription during development." (PMID 25969726, 2015). "One leading theory of the pathogenesis of Alzheimer’s disease (AD) considers the sequential cleavage of the amyloid precursor protein (APP) by β- and γ-secretases to release amyloidogenic peptides to be the initiating and driving event in this neurodegenerative condition." (PMID 26064192, 2015). "In models of Alzheimer disease produced by overexpression of APP/PS1 or human APP, CX3CR1 knockout results in decreased levels of pro-inflammatory cytokines Tumor Necrosis Factor (TNF) and monocyte chemotactic protein 1 (CCL2) but increased Interleukin 1-beta (IL1β)." (PMID 26469270, 2015). "The unexpected link between APP and endosomal phosphoinositide metabolism may suggest a novel and surprising mechanism for neurodegeneration in Alzheimer's disease." (PMID 26125944, 2015). "Particularly, in Alzheimer’s disease, the patient has two important lesions, extracellular amyloid plaques, and intraneuronal neurofibrillary tangles formed by Aβ peptide, which is generated through sequential cleavage of amyloid precursor protein (APP)." (PMID 26225966, 2015). "Our finding that APP regulates the PIKfyve complex in C. elegans in vivo hints at a novel molecular mechanism for neurodegeneration in Alzheimer's disease in which aberrant processing of APP by beta and gamma secretases would preclude APP from binding to and activating the PIKfyve complex." (PMID 26125944, 2015). "We begin with a brief account of the genetics of early-onset familial Alzheimer's disease and the discovery of the APP gene, then move on to the patents, and finally discuss patent assignment and enforcement: the resolution of many infringement lawsuits, and the lessons learned." (PMID 26594384, 2015). "It is conceivable that loss-of-APP function rather than the toxic gain-of-function of beta amyloid drives neurodegeneration in Alzheimer's disease." (PMID 26125944, 2015). "APP cleavage products are involved in cytotoxic pathways and could contribute to pathological processes leading to neurodegeneration in Alzheimer's disease (AD)." (PMID 26600047, 2015). "Moreover, APP triplication appears to be a key factor that favors the almost unavoidable development of Alzheimer's disease in adults with DS." (PMID 26500515, 2015). "APP promoter hypomethylation in Alzheimer’s disease patients." (PMID 25774124, 2015). "Processing of APP to Aβ‐peptide results in the pathology of Alzheimer's disease." (PMID 25712587, 2015). "The potential effects of Alzheimer’s disease pathology on M18 levels were further modeled using APP23 transgenic mice, which overexpress a pathogenic variant of the human amyloid precursor protein (APP)." (PMID 26628003, 2015).
Alzheimer disease (continued). "APP may be processed into pathological forms of β-amyloid in lysosomes, with subsequent exocytosis depositing APP in the brain, thus forming the pathological β-amyloid plaques typical of Alzheimer’s disease." (PMID 26657340, 2015). "Our findings establish an unexpected role for APP in the regulation of endosomal phosphoinositide metabolism with dramatic consequences for endosomal biology and important implications for our understanding of Alzheimer's disease." (PMID 26125944, 2015). "Alzheimer’s disease (AD) involves aberrant protein processing and is characterized by excessive accumulation of β-amyloid (Aβ), which is derived from cleavage of the amyloid precursor protein (APP)." (PMID 26244977, 2015). "The amyloid cascade hypothesis assumes that Alzheimer’s disease is a primary amyloidosis originated from altered processing of amyloid precursor protein (APP) which drives production of amyloid-β (Aβ)." (PMID 26018424, 2015). "While it is clear that APP's processing is intimately linked with Alzheimer's disease there is currently no clear mechanistic model for the molecular events that lead to the induction and progression of this disease." (PMID 26125944, 2015). "An overview of a variety of processes affected by an increased dose of APP protein and/or its derivative Aβ peptides, that may contribute in DS to pathogenesis of Alzheimer's dementia or cognitive impairment (I.D.), or both." (PMID 26648852, 2015). "This hypothesis suggests that the central event in Alzheimer's disease pathology is the deposition in the brain of amyloid-β, a fragment of a transmembrane protein, APP." (PMID 26594384, 2015). "For example, amyloid precursor protein (APP) plays a central role in Alzheimer’s disease." (PMID 26569330, 2015). "We hope that a better understanding of APP trafficking may yield a promising therapeutic target for Alzheimer’s disease." (PMID 26170135, 2015). "Given the link of APP to Alzheimer’s disease, alterations of this synaptic role of APP could contribute to dementia." (PMID 26551565, 2015). "In the continuing search for new cerebrospinal fluid (CSF) biomarkers for Alzheimer’s disease (AD), reasonable candidates are the secretase enzymes involved in the processing of the amyloid precursor protein (APP), as well as the large proteolytic cleavage fragments sAPPα and sAPPβ." (PMID 26082753, 2015). "Alzheimer's disease (AD) is a complex, multifactorial disease with a number of leading mechanisms, including neuroinflammation, processing of amyloid precursor protein (APP) to amyloid β peptide, tau protein hyperphosphorylation, relocalization, and deposition." (PMID 26041981, 2015). "The amyloid precursor protein (APP) plays a central role in Alzheimer’s disease (AD)." (PMID 26274614, 2015). "Amyloid-β precursor protein (APP) present in both astrocytes and endothelial cells, may contribute to the Alzheimer’s disease pathology, and is positively regulated, in part, by IL-1." (PMID 25311416, 2014). "APP is ubiquitously expressed in a broad spectrum of cell types including non-neuronal cells, while the nature of APP has been mainly studied in neuronal cells due to its pathological significance in Alzheimer disease." (PMID 25491510, 2014). "Amyloid precursor protein (APP) is centrally involved in the pathogenesis of Alzheimer’s disease." (PMID 24404197, 2014). "Interestingly, these disorders have also been reported to be associated with over-expression of other genes such as α synuclein gene in some cases of Parkinson's disease and amyloid precursor protein (APP gene) in Alzheimer's disease." (PMID 24649381, 2014). "Such a circumstance would be where pH and the anion gap are altered, such as within a hypoxic environment and hypophosphatemia, or when apo-TF and/or APP/sAPPα are in limited supply, such as with anemia of chronic inflammation and Alzheimer’s disease respectively." (PMID 25464026, 2014).
Alzheimer disease (continued). "Transgenic (Tg) mice that overexpress mutant familial Alzheimer's disease (AD) amyloid precursor protein (APP) genes have contributed to an understanding of dementia pathology and support the amyloid cascade hypothesis." (PMID 25025046, 2014). "In the amyloidogenic pathway APP is sequentially cleaved by β-secretase followed by γ-secretase to produce the amyloid-beta product, well known for its involvement in neuronal degeneration in Alzheimer's disease." (PMID 25177267, 2014). "To elucidate the potential contributions of APP to the Aβ diurnal pattern and the balance of the α- and β- pathways in APP processing, we measured APP proteolytic products over 36 hours in human cerebrospinal fluid from cognitively normal and Alzheimer's disease participants." (PMID 24646516, 2014). "APP is a cell surface receptor involved in Alzheimer’s disease and cerebral amyloid angiopathy." (PMID 25433733, 2014). "The neuropathological hallmarks of Alzheimer's disease (AD) include senile plaques of β-amyloid (Aβ) peptides (a cleavage product of the Amyloid Precursor Protein, or APP) and neurofibrillary tangles (NFT) of hyperphosphorylated Tau protein assembled in paired helical filaments (PHF)." (PMID 24574966, 2014). "Amyloid-β precursor protein (APP) plays a central role in pathogenesis of Alzheimer's disease." (PMID 24932508, 2014). "In double transgenic AD mouse (AβPP/PS1), NBP reduced Aβ production while, in triple transgenic mouse (3xTg-AD), NBP intervened with APP processing and alleviated oxidative stress, implicating its potential use in Alzheimer's disease and other forms of dementia." (PMID 24949079, 2014). "Given that elevated APP protein expression can elicit Alzheimer’s disease (AD) in patients and model systems, we evaluated whether FMRP expression might be altered in Alzheimer’s autopsy brain samples and mouse models compared to controls." (PMID 25452762, 2014). "Mitochondrial dysfunction is an established phenomenon in Alzheimer’s disease (AD), but the causes and role of PS1, APP, and APP’s cleavage products in this process are largely unknown." (PMID 24304563, 2014). "APP is of special interest because of its possible role in Alzheimer’s disease." (PMID 23977245, 2013). "The amino acid aggregates of Aβ peptides forming the major component of plaques characteristic of Alzheimer's Disease (AD) result from N-terminal cleavage of the amyloid precursor protein (APP) mediated by an aspartyl protease referred to as Beta-site APP Cleaving Enzyme 1 (BACE1)." (PMID 24381583, 2013). "Processing of amyloid precursor protein (APP) by β- and γ-secretase activities produces β-amyloid (Aβ) peptide, which accumulates in extracellular senile plaques present in brain of patients with Alzheimer disease (AD)." (PMID 23554170, 2013). "APP is the subject of intense research because of genetic and biochemical links to Alzheimer's disease (AD), whereby the proteolytic processing of APP generates the Amyloid Beta peptide whose accumulation in the brain is widely thought to induce neurodegeneration." (PMID 23690751, 2013). "Proteolytic cleavage at any of these sites leads to a decrease in the generation of α-secretase cleaved secreted APP, which has both anti-apoptotic and neuroprotective properties, and thus may contribute to neurodegeneration in Alzheimer's disease." (PMID 23469123, 2013). "ApoE, ApoE receptors and APP cooperate in the pathogenesis of Alzheimer’s disease." (PMID 23986861, 2013). "In addition to Alzheimer's disease, other neurological disorders including Down's syndrome, autism, and epilepsy are characterized by elevated expression of APP." (PMID 24376773, 2013). "Expression of two genes in particular, amyloid beta (A4) precursor protein (APP) and microtubule associated protein tau (MAPT), which are normally associated with Alzheimer’s Disease, was found to be significantly higher in the maters relative to the non-maters." (PMID 23874981, 2013).
Alzheimer disease (continued). "Alzheimer’s disease (AD) is characterized by the accumulation of aggregated amyloid-β (Aβ) peptide species derived from successive proteolytic cleavages of the β-amyloid precursor protein (APP)." (PMID 24376644, 2013). "As such, APP represents a key axonal transport cargo in Alzheimer's disease." (PMID 23825109, 2013). "Recent studies have shown that NPC disease exhibits intriguing parallels with Alzheimer’s disease, including the presence of neurofibrillary tangles and increased levels of amyloid precursor protein (APP)-derived β-amyloid (Aβ) peptides in vulnerable brain neurons." (PMID 23382922, 2013). "It has been shown that the abnormal processing of APP by β and γ-secretase enzymes is a key event in the development of Alzheimer's disease (AD) neuropathology, resulting in an increase in the generation of the 42 amino acid form of Aβ peptide which aggregates to form the insoluble amyloid plaques." (PMID 23497276, 2013). "As will be discussed in the subsequent paragraphs, an association between APP accumulation and Aβ formation in injured axons, post-injury plaque deposition and the development of Alzheimer’s disease (AD) has not been firmly established." (PMID 23805125, 2013). "Amyloid precursor protein (APP) is a major etiologic agent in Alzheimer disease (AD)." (PMID 23776568, 2013). "Our findings indicate that locomotor hyperactivity displayed by the tet-off APP transgenic mice and several other transgenic models of Alzheimer’s disease may result from overexpression of mutant APP during postnatal brain development." (PMID 22709352, 2012). "Alzheimer's disease (AD) is characterized neuropathologically by progressive brain deposition of the amyloid β peptide (Aβ), which is generated by proteolytic cleavage of amyloid precursor protein (APP) by β- and γ-secretases." (PMID 22558227, 2012). "Zink-ions (Zn2+) inhibit the ferroxidase activity of APP and abnormal exchange of cortical zinc may link APP to iron accumulation in Alzheimer’s disease." (PMID 23055972, 2012). "Alzheimer's disease (AD) is a neurodegenerative disorder characterized by the deposition of β-amyloid plaques composed primarily of the amyloid-β peptide, a cleavage product of amyloid precursor protein (APP)." (PMID 22363792, 2012). "We suggest tau enhances the level of APP/AICDc58 and APP/c31-induced cell death, and could contribute to progression of Alzheimer’s disease." (PMID 23028730, 2012). "Thus an interaction of APP with PrP has the potential to be consequential at several nodes of Alzheimer Disease etiology." (PMID 23236467, 2012). "APP transgenic mice also recapitulate the characteristic cognitive symptoms of Alzheimer’s disease." (PMID 22709352, 2012). "APLP2, like APP, has been implicated in Alzheimer’s disease, although APLP2’s sequence does not include the β-amyloid peptide found within APP." (PMID 22797723, 2012). "In addition to tau hyperphosphorylation, another pathological characteristic of Alzheimer's disease is the deposition of toxic Aβ peptides, aberrant cleavage products of amyloid precursor protein (APP), and formation of amyloid plaques in the brain." (PMID 23029362, 2012). "In addition, in animal models of Alzheimer's disease, in which mutant human APP is expressed, the effect of toxic Aβ peptide has been assessed in the retina." (PMID 22279552, 2012). "Successive proteolytic processing of APP by β- and γ- secretase enzymes generates the amyloid-β peptide, a primary component of amyloid plaques, which are thought to be central to the etiology of Alzheimer's disease (AD)." (PMID 23236292, 2012). "Our study reports a unique in vivo interdependence between APP and PRP loss-of-function, detailing a biochemical interaction that considerably expands the hypothesized roles of PRP in Alzheimer Disease." (PMID 23236467, 2012).